MIGA1 (mitoguardin 1)
Description:
Regulator of mitochondrial fusion: acts by forming homo- and heterodimers at the mitochondrial outer membrane and facilitating the formation of PLD6/MitoPLD dimers. May act by regulating phospholipid metabolism via PLD6/MitoPLD.
Synonyms: FAM73A; FLJ35093
Tractability: Antibody: its Gene Ontology location is reachable by antibodies, with high confidence; UniProt predicts a signal peptide or a membrane-spanning region. PROTAC: ubiquitination databases record sites on it.
Gene: Protein-coding gene on chromosome 1 (77,779,624 to 77,879,540, forward strand). Ensembl gene ENSG00000180488.
Subcellular location: Mitochondrion outer membrane
Subcellular location (Human Protein Atlas): Mitochondria
Pathways (Reactome):
Metabolism: Synthesis of PA
Gene Ontology:
Molecular function: protein binding; protein heterodimerization activity; protein homodimerization activity
Biological process: mitochondrial fusion
Cellular component: mitochondrial outer membrane; mitochondrion; plasma membrane
Genetic constraint (gnomAD): Loss-of-function variants: 27 observed, 36.19 expected, observed/expected ratio (o/e) 0.75, 90% interval 0.55 to 1.03. The upper end of that interval is the gene's LOEUF score, 1.03, which puts it in group 4 of 6, group 1 being the genes least tolerant of losing a copy. Missense variants: 371 observed, 375.33 expected, observed/expected ratio (o/e) 0.99, 90% interval 0.91 to 1.08. Synonymous variants: 137 observed, 128.77 expected, observed/expected ratio (o/e) 1.06, 90% interval 0.93 to 1.23.
Homologues: Orthologues: chimpanzee MIGA1 (99% identical), macaque MIGA1 (99% identical), pig MIGA1 (95% identical), rabbit MIGA1 (95% identical), dog MIGA1 (91% identical), guinea pig MIGA1 (87% identical), mouse Miga1 (85% identical), rat Miga1 (85% identical), tropical clawed frog miga1 (66% identical), zebrafish miga1 (61% identical), Drosophila melanogaster Miga (28% identical), Caenorhabditis elegans miga-1 (22% identical). Paralogues in human: MIGA2 (39% identical).
Diseases named in the same sentence as MIGA1 in open-access papers:
MIGA1 is named in the same sentence as 9 diseases in open-access papers, as found by Europe PMC text mining. Sharing a sentence is not in itself a finding about the gene and the disease. The quoted sentences say what the papers report.
Autoimmunity (1 paper, 2024). The occurrence of an immune reaction against the organism's own cells or tissues. "Moreover, mIgA1 has been reported to activate cytotoxic CD8+ T cells, and an aberrant glycosylation profile has been reported to increase the pro-inflammatory effect of these molecules, leading to greater disease severity in autoimmunity." (PMID 39358866, 2024).
hyperandrogenism (1 paper, 2023). Excessive secretion of androgens from the adrenal glands or gonads. "MIGA1 or MIGA2 (MIGA1,-2) expression has been implicated in hyperandrogenism in patients with PCOS." (PMID 38012141, 2023).
infection (1 paper, 2020). The state of being infected such as from the introduction of a foreign agent such as serum, vaccine, antigenic substance or organism. "Furthermore, genes involved in mitochondrial activity, such as MIGA-1, were differentially expressed after basolateral infection of HIBCPP cells compared to control conditions." (PMID 32872518, 2020).
MIGA1 also shares sentences with these, for which no sentence is quoted: gastric cancer (1 paper); neuroblastoma (1); Obesity (1); ovarian carcinoma (1); polycystic ovary syndrome (1); serous ovarian cancer (1).